CCR2 (C-C motif chemokine receptor 2)
Diseases named in the same sentence as CCR2 in open-access papers (continued):
Sharing a sentence is not in itself a finding about the gene and the disease.
vasculitis (6 papers, 2012 to 2025). "The experimental model of vasculitis reportedly underlies the interaction between the CCR2 expressed in monocytes and the CCL2 induced by the NOD1-dependent signaling in EC." (PMID 31316950, 2019). "The top 10 GSEA HPO results revealed that CCR2 was mostly relevant for abnormalities in a variety of immune cells, including abnormal granulocyte count, B lymphocytopenia, vasculitis, abnormal lymphocyte morphology, and abnormal immune system morphology." (PMID 37760894, 2023). "Both genetic deficiency of the MCP-1 receptor (CCR2) or MCP-1/CCL2 antagonism improved LN and vasculitis in MRL/lpr mice." (PMID 34307414, 2021). "While CCR2 and GM-CSF play an indispensable role in its pathogenesis, T and B cells are also involved in the vasculitis." (PMID 31316950, 2019). "Mechanistically, both T and B cells were required for the induction of vasculitis, a role that was directly modulated by CCR2." (PMID 23074996, 2012). "Collectively, our findings provide novel insights into the role of CCR2 in the pathogenesis of vasculitis as seen in KD and other types of vasculitis, and highlighting novel therapeutic targets specifically for individuals resistant to first-line treatments." (PMID 23074996, 2012). "Collectively, our findings provide novel insights into the role of CCR2 in the pathogenesis of vasculitis as seen in KD and highlight novel therapeutic targets, specifically for individuals resistant to first-line treatments." (PMID 23074996, 2012). "The data also suggest that CCR2 modulates the role of T and B cells in the induction of vasculitis." (PMID 23074996, 2012). "CCR2-deficient mice are resistant to the development of CAWS-induced vasculitis, suggesting that chemokines and their receptors might be attractive new targets for vasculitis treatments." (PMID 33150252, 2020). "It recruits inflammatory cells (e.g., Monocytes and neutrophils) via the CCRI pathway through its receptor CCR2, and activates the Dectin-2/NLRP3 inflammasome to induce IL-1β, driving vasculitis in KD models." (PMID 40455761, 2025). "As expected, due to the milder vasculitis phenotype in Ccr2−/− mice, serum MPO level post-injection in these mice was lower than in Ccr2+/+ mice." (PMID 23074996, 2012). "In addition, expression of CXCR2 and CCR2 in the aortic root and coronary arteries is increased in CAWS-induced vasculitis mice, suggesting that CXCR2 promotes neutrophil recruitment and CCR2 controls monocyte infiltration." (PMID 33150252, 2020).
acute liver failure (5 papers, 2014 to 2024). Rapid deterioration of liver function causing encephalopathy and coagulopathy. "CCR2-overexpressing MSCs enhances the targeted migration of MSCs to damaged liver and improves the therapeutic effect of acute liver failure." (PMID 38213743, 2024). "Targeting macrophage ASK1 (ASK1 inhibitor Selonsertib), CCR5 (CCR5 antagonist Maraviroc), CCR2 (CCR2/5 due-inhibitor Cenicriviroc), and CSF1 (CSF1R antibody and inhibitor) have been proved to have a good therapeutic effect on acute liver failure." (PMID 36225585, 2022).
allergic asthma (5 papers, 2004 to 2025). A asthma with a basis in a pathological type I hypersensitivity reaction. "CCR2-deficient mice have been found to have altered inflammatory and physiologic responses in some models of experimental allergic asthma, but the role of CCR2 in contributing to inflammation and airway hyperreactivity appears to vary considerably between models." (PMID 15377395, 2004). "To test whether MCP-1 and CCR2 are each required for the development of experimental allergic asthma, we applied an Aspergillus antigen-induced model of Th2 cytokine-driven allergic asthma associated with airway fibrosis to mice deficient in either MCP-1 or CCR2." (PMID 15377395, 2004). "To test this hypothesis, we subjected mice deficient in either MCP-1 or CCR2 to an Aspergillus antigen model of Th2-cytokine-driven allergic asthma associated with significant airway fibrosis and measured pulmonary inflammation, cytokine production, AHR and fibrosis." (PMID 15377395, 2004). "More interestingly, blockade of CCL2/CCR2 signaling provides protective immunity in murine models of OVA‐induced allergic asthma." (PMID 39988712, 2025). "Our results stand in contrast to some previous reports showing important roles for MCP-1 or CCR2 in other models of allergic asthma." (PMID 15377395, 2004). "We hypothesized that MCP-1 and its receptor, CCR2, are independently required for the development of Aspergillus-antigen-induced allergic asthma." (PMID 15377395, 2004). "In this study, we hypothesized that the effects of MCP-1 are mediated through CCR2 and that MCP-1 and CCR2 are independently required for the development of experimental allergic asthma." (PMID 15377395, 2004). "Previous studies involving other models of allergic asthma applied to CCR2-deficient mice did not examine whether airway fibrosis occurred in these models or whether development of fibrosis was dependent on CCR2 expression." (PMID 15377395, 2004). "To verify if increased levels of MCP-1 and percentages of CCR2+ T cells are characteristic for pediatric ILD, we analyzed these markers in ten selected age-matched children with well-characterized allergic asthma who are described in detail in a previous study." (PMID 16095529, 2005).
amyloid (5 papers, 2012 to 2021). "Indeed, transplantation of competent CCR2 hematopoietic stem cells is able to counteract amyloid pathology and to restore mnesic capacity in 6-month-old APPSwe/PS1 and APPSwe/PS1/CCR2−/− mice." (PMID 23125823, 2012). "It has been suggested that PVM requires the C-C chemokine receptor type 2 (CCR2), a receptor involved in the regulation of macrophage migration and infiltration, to remove amyloid from the brain, since APPswe CCR2−/− mice showed a drastic impairment in Aβ clearance and amplified CAA." (PMID 31847365, 2019). "We have previously shown that sustained expression of IL-1β in the hippocampus of APP/PS1 mice decreases amyloid plaque burden independent of recruited CCR2+ myeloid cells, suggesting resident microglia as the main phagocytic effectors of IL-1β-induced plaque clearance." (PMID 31822279, 2019). "However, disrupting CCR2 signaling and recruitment of BMD-mononuclear phagocytes did not alter the ability of IL-1β to reduce amyloid plaque burden." (PMID 31822279, 2019).
amyotrophic lateral sclerosis (5 papers, 2012 to 2021). Amyotrophic lateral sclerosis (ALS) is a neurodegenerative disease characterized by progressive muscular paralysis reflecting degeneration of motor neurons in the primary motor cortex, corticospinal tracts, brainstem and spinal cord. "Macrophages expressing C–C chemokine receptor type 2 (CCR2) infiltrate the central and peripheral neural tissues of amyotrophic lateral sclerosis (ALS) patients." (PMID 34385589, 2021). "Reports from this mouse strain show no detectable CCR2 in resident cells of the lumbar spinal cord in healthy mice, while CCR2 expression expanded from infiltrating monocytes to microglia and neurons with the progression of amyotrophic lateral sclerosis." (PMID 34857006, 2021). "It remains controversial whether circulating monocytes expressing CCR2 infiltrate the central nervous system (CNS) and contribute to pathogenicity of amyotrophic lateral sclerosis (ALS)." (PMID 32349774, 2020).
autoimmune myocarditis (5 papers, 2009 to 2025). Autoimmune myocarditis is an autoimmune disease that affects the heart. "In an in vivo model for autoimmune myocarditis in mice, which were either genetically deficient in CCR2 or treated with siRNA targeting CCR2, reduced inflammation with preserved LVEF was observed compared to control." (PMID 41166051, 2025). "Further, mice deficient in MCP-1 or CCR2 are resistant to the development of experimental-induced autoimmune myocarditis." (PMID 19587788, 2009). "Leuschner reported that mice silenced CCR2 exhibit a reduced inflammation in autoimmune myocarditis." (PMID 37069636, 2023). "Elevated levels of CCR1, CCR2, and CCR5 expression in the heart of A/J mice that were immunized with cardiac troponin I to develop autoimmune myocarditis were previously reported." (PMID 34944410, 2021). "When activated, this pathway protected organs, including heart, from the consequences of the ischemic injury, decreased levels of CCL2 and LIX after reperfusion injury, and downregulated the expression of CCL2, CCL4, CCL5, CCR1, CCR2, and CCR5 in murine autoimmune myocarditis." (PMID 27242392, 2016).
focal segmental glomerulosclerosis (5 papers, 2018 to 2025). A renal disorder characterized by sclerotic lesions in the glomeruli. "Similarly, clinical trials involving CCX140-B, a CCR2 antagonist, have reported decreased proteinuria in patients with DKD and focal segmental glomerulosclerosis (FSGS), suggesting a potential renoprotective effect." (PMID 41050663, 2025).
interstitial lung disease (5 papers, 2005 to 2025). A diverse group of lung diseases that affect the lung parenchyma. "We are presenting two cases of autosomal‐recessive CCR2 deficiency suffering from interstitial lung disease (ILD) presenting with cystic lung destruction." (PMID 40432300, 2025). "CCL2, a ligand for CCR2, is elevated in early systemic sclerosis and is a biomarker for progression of interstitial lung disease in these patients." (PMID 33407866, 2021). "Moreover, surface CCR5 was reduced on the monocytes from SSc patients with interstitial lung disease but also, along with CCR2, negatively correlated with the use of analgesics/anti-inflammatory drugs and immunosuppressants." (PMID 35216350, 2022).
pancreatic adenocarcinoma (5 papers, 2017 to 2024). "Another CCR2 inhibitor CCX872 has also been evaluated in combination with FOLFIRINOX in patients with pancreatic adenocarcinoma (NCT02345408)." (PMID 35122833, 2022). "PF-04136309 (CCR2 targeting agent) in combination with FOLFIRINOX has improved survival in patients with pancreatic adenocarcinoma (NCT01413022)." (PMID 35122833, 2022). "Dual-blockade CCR2 plus CXCR2 with specific antagonists reduces tumor-infiltrating myeloid cells and enhances chemotherapeutic responses in pancreatic adenocarcinoma patients and animal models." (PMID 31780645, 2019).
pulmonary hypertension (5 papers, 2018 to 2025). Increased pressure within the pulmonary circulation due to lung or heart disorder. "CCR2-deficient mice have an expected decrease in recruitment of inflammatory monocytes to the lung during chronic hypoxic stress, associated with worsening of pulmonary hypertension." (PMID 30081463, 2018). "Interestingly, in mice exposed to hypoxia or SUGEN-induced pulmonary hypertension, targeting both CCR2 and CCR5 prevented or reversed PH more efficiently than targeting either receptor alone." (PMID 36246557, 2022). "Meanwhile, macrophage NLRP3 activates CCR2+ monocyte-derived macrophages, increases NLRP3 expression, and contributes to pulmonary hypertension-induced ventricular failure." (PMID 39935606, 2025). "Additionally, other cell-surface chemokine receptors commonly expressed by Mo-MDSC, such as CCR2 and CX3CR1, are highly expressed in circulating immune cells accumulating within the lungs of mice with chronic hypoxia-induced pulmonary hypertension." (PMID 30081463, 2018).
retinitis pigmentosa (5 papers, 2013 to 2023). Retinitis pigmentosa (RP) is an inherited retinal dystrophy leading to progressive loss of the photoreceptors and retinal pigment epithelium and resulting in blindness usually after several decades. "Recent evidence shows that CCR2+ monocyte recruitment also plays an important role in photoreceptor degeneration in models of retinitis pigmentosa, photo-oxidative stress, and in the carboxyethylpyrrole-immunization induced model of AMD." (PMID 24142887, 2013). "The infiltration of inflammatory monocytes was shown to be CCR2-dependent in inflammatory diseases, including several retinal disorders such as retinal injury, atrophic age-related macular degeneration and photoreceptor degeneration in models of retinitis pigmentosa." (PMID 36698021, 2023).
schistosomiasis (5 papers, 2014 to 2023). An infectious disease caused by parasitic trematodes of the genus Schistosoma that colonize human blood vessels and release eggs that can cause granulomatous reactions leading to acute (swimmer's itch or acute schistosomiasis syndrome) or chronic disease. "In conclusion, our results provide further understanding of the pathogenesis of human schistosomiasis, and the role of CCR2+ monocytes and CXCR2+ NKT cells in schistosomiasis requires further study." (PMID 37817226, 2023). "Our findings using CCR2-DTR mice revealed a critical role for monocytes for survival during acute schistosomiasis." (PMID 25144366, 2014). "To further explore the importance of monocyte-derived macrophages in schistosomiasis, we examined the outcome of infection in CCR2-Diphtheria Toxin Receptor (DTR) mice, in which cells that express CCR2 also express DTR and can be acutely deleted by the injection of DT." (PMID 25144366, 2014). "This preliminary study suggests that the increased presence of CCR2 + monocyte and CXCR2 + NKT cells might participate in the progression of schistosomiasis." (PMID 37817226, 2023). "In mice, which are an established in vivo experimental model of human schistosomiasis, monocytes have been defined on the basis of expression of the surface markers Ly6C, CD115 and the chemokine receptor CCR2, and are thought to be selectively recruited to inflamed tissues." (PMID 24762736, 2014).
tuberculosis (5 papers, 2017 to 2024). A chronic, recurrent infection caused by the bacterium Mycobacterium tuberculosis. "Moreover, type I IFN leads to a CCR2-dependent accumulation of permissive lung MΦ and neutrophils in mice, which promotes tuberculosis exacerbation." (PMID 33795674, 2021).
Venous thrombosis (5 papers, 2021 to 2026). Formation of a blood clot (thrombus) inside a vein, causing the obstruction of blood flow. "Targeted deletion of CCR2 in the mice model of venous thrombosis showed association with impairment of thrombi resolution." (PMID 33679991, 2021). "Gas6 can amplify endothelial cell activation through TF expression, collect platelets and leukocytes to the endothelial cell membrane, and promote the recruitment of monocytes through a CCR2/CCL2-dependent mechanism during venous thrombosis." (PMID 35444662, 2022). "In a murine model of venous thrombosis, the CCR2 expression in monocytes could indicate a pro-inflammatory phenotype is present and that the increase in this receptor and the consequent cell recruitment to venous thrombi improved thrombus clearance." (PMID 40020285, 2025).
acute monocytic leukemia (4 papers, 2015 to 2025). Acute monoblastic leukemia (AML-M5), is one of the most common subtypes of acute myeloid leukemia (AML) that is either comprised of more than 80% of monoblasts (AML-M5a) or 30-80% monoblasts with (pro)monocytic differentiation (AML-M5b). "Of note, the detection of CCR2 mRNA in an acute monocytic leukemia cell line (THP1) known to express CCR2 demonstrated the validity of our system of analysis." (PMID 28698717, 2017). "THP-1 is derived from a human acute monocytic leukemia, displays monocytic markers, has phagocytic activity and expresses CCR2, indicating that it is a model for TAMs." (PMID 26327448, 2015).
alveolitis (4 papers, 2011 to 2024). "Observations revealed a decisive role of the CCL2/CCR2 axis in driving M1 macrophage polarization, and this type of macrophages was confirmed to boost alveolitis in leading myofibroblast activation." (PMID 38273656, 2024). "In endotoxin-mediated ARDS, bone marrow-derived blood-borne monocytes expressing CCR2 are involved in amplifying neutrophilic alveolitis." (PMID 38596679, 2024). "In combination with data from scRNA-seq of patients and a murine IPF model, a decisive role of CCL2/CCR2 axis in driving M1 macrophage polarization was revealed, and M1 macrophage was further confirmed to boost alveolitis in leading myofibroblast activation." (PMID 38273656, 2024).
atopic dermatitis (4 papers, 2013 to 2026). "In contrast, an abundance of eosinophils and mast cells accumulated in the ears of CCR2−/− mice suggesting the development of a Th2-type immune response resembling atopic dermatitis." (PMID 23472158, 2013). "Similar to mice injected intradermally with TSLP or genetically engineered to overexpress TSLP in keratinocytes, the increased TSLP expression seen in CCR2−/− mice correlated with development of an atopic dermatitis-like cutaneous inflammation." (PMID 23472158, 2013).
autoimmune encephalitis (4 papers, 2012 to 2024). Inflammation of the brain secondary to an immune response triggered by the body itself. "Deficiencies in Ccr2 impair monocyte recruitment to tissues in disease models ranging from arthrosclerosis and autoimmune encephalitis, to choroidal neovascularization." (PMID 25595590, 2015). "Studies in the Experimental Autoimmune Encephalitis (EAE) model using CCR2−/− mice indicate that CCR2 plays a crucial role in recruitment of monocytes, and these mice are resistant to EAE." (PMID 22731103, 2012).
bone cancer (4 papers, 2017 to 2025). A primary or metastatic malignant neoplasm affecting the bone or articular cartilage. "CCR2 antagonism also led to significant attenuation of bone cancer pain." (PMID 41008336, 2025). "Moreover, MCP-1 induced hyperalgesia and anti-MCP-1 or CCR2 agonist attenuated hyperalgesia in animals with bone cancer when applied intrathecally." (PMID 28542626, 2017). "Among them, BDNF and TNF produced in bone tumor metastasis metabolism-α, MCP-1 and CCR2 can activate TRPA1." (PMID 35295475, 2021).
bone metastasis (4 papers, 2021 to 2023). Transfer of a neoplasm from its primary site to bones. "CD204hiIL-4Rhi macrophages are clarified as bone metastasis–associated macrophages, most of which are derived from Ly6C+CCR2+ classical monocytes recruited by CCR2." (PMID 37443711, 2023). "A phase II clinical trial (NCT01015560) of the anti-CCR2 antibody MLN1202 showed efficacy in 14% of patients with bone metastasis." (PMID 36241867, 2022). "A distinct approach to CCL2/CCR2 interference, was hindering CCR2 using MLN1202 in bone metastasis." (PMID 34566995, 2021).
depression (4 papers, 2014 to 2022). "Among them, chemokine CCL2 and its main receptor CCR2 have become candidate mediators of abnormal brain-immune system dialogue in depression." (PMID 34031863, 2021). "This highlights the importance of the CCL2/CCR2 signaling and suggests a possible link with depressive disorders." (PMID 25065370, 2014).
diffuse large B-cell lymphoma (4 papers, 2020 to 2024). "Overexpression of CCR2 has been identified as a poor prognostic predictor in diffuse large B-cell lymphoma (DLBCL)." (PMID 39015296, 2024). "Also, the blockade of CCR2 expression reduces tumor growth and inhibits the proliferation of cancer cells by influencing the PI3K/Akt and p38 MAPK signaling pathway in DLBCL (diffuse large B-cell lymphoma)." (PMID 37325423, 2023). "Another study demonstrated that CCR2 inhibition improves apoptosis by influencing PI3K/AKT and p38MARK signaling pathway in DLBCL (diffuse large B-cell lymphoma) cell lines such as SUDHL-2 and OCI-Ly8." (PMID 37325423, 2023).